GEMIN8 (gem nuclear organelle associated protein 8)
Description:
The SMN complex catalyzes the assembly of small nuclear ribonucleoproteins (snRNPs), the building blocks of the spliceosome, and thereby plays an important role in the splicing of cellular pre-mRNAs. Most spliceosomal snRNPs contain a common set of Sm proteins SNRPB, SNRPD1, SNRPD2, SNRPD3, SNRPE, SNRPF and SNRPG that assemble in a heptameric protein ring on the Sm site of the small nuclear RNA to form the core snRNP (Sm core). In the cytosol, the Sm proteins SNRPD1, SNRPD2, SNRPE, SNRPF and SNRPG are trapped in an inactive 6S pICln-Sm complex by the chaperone CLNS1A that controls the assembly of the core snRNP. To assemble core snRNPs, the SMN complex accepts the trapped 5Sm proteins from CLNS1A forming an intermediate. Binding of snRNA inside 5Sm triggers eviction of the SMN complex, thereby allowing binding of SNRPD3 and SNRPB to complete assembly of the core snRNP.
Synonyms: FAM51A1; FLJ20514
Tractability: PROTAC: ubiquitination databases record sites on it.
Gene: Protein-coding gene on chromosome X (13,998,099 to 14,029,928, reverse strand). Ensembl gene ENSG00000046647.
Subcellular location: Nucleus, gem; Cytoplasm
Subcellular location (Human Protein Atlas): Cytosol; Nucleoplasm
Pathways (Reactome):
Disease: SARS-CoV-2 modulates host translation machinery
Metabolism of RNA: snRNP Assembly
Gene Ontology:
Molecular function: protein binding
Biological process: spliceosomal snRNP assembly
Cellular component: cytoplasm; cytosol; nucleus; SMN complex; SMN-Sm protein complex; nucleoplasm; Gemini of Cajal bodies
Homologues: Orthologues: chimpanzee GEMIN8 (99% identical), macaque GEMIN8 (95% identical), guinea pig GEMIN8 (71% identical), rabbit GEMIN8 (70% identical), rat Gemin8 (68% identical), mouse Gemin8 (67% identical), pig GEMIN8 (65% identical), tropical clawed frog gemin8 (47% identical), zebrafish gemin8 (42% identical), Caenorhabditis elegans F10E9.5 (20% identical).
Diseases named in the same sentence as GEMIN8 in open-access papers:
GEMIN8 is named in the same sentence as 1 disease in open-access papers, as found by Europe PMC text mining. Sharing a sentence is not in itself a finding about the gene and the disease.
GEMIN8 shares sentences with these, for which no sentence is quoted: tumor (1 paper).